PTGS2 (prostaglandin-endoperoxide synthase 2)
Diseases named in the same sentence as PTGS2 in open-access papers (continued):
Sharing a sentence is not in itself a finding about the gene and the disease.
cancer (continued). "For example, TOP2A, LAG3, SLAMF7, and PTGS2 are established or promising key targets for cancer treatments and immunotherapy." (PMID 38746418, 2024). "Our preliminary data suggest nuclear βPix binds β-catenin/TCF4 transcription complexes, augmenting key β-catenin target gene expression, e.g., PTGS2, important for cancer progression." (PMID 37805544, 2023). "We discovered that MDM2, PTGS2, EGFR, and VEGFA are the key genes regulated by JCF and closely associated with the development of cancer." (PMID 37361218, 2023). "Thousands of mRNAs are ELAVL1 targets, including factors fostering diverse cancer traits such as proliferation (cyclins A2, B1, D1, and E1), angiogenesis (HIF1a, PTGS2, and VEGFA), survival (BCL2 and MCL1), and invasion (MMP9 and SNAI1)." (PMID 37298909, 2023). "In this study, we predicted that PTGS2, iNOS, and MMPs, which are key OA therapeutic targets of PL, were mainly related to cancer pathways." (PMID 38328576, 2023). "From the network pharmacology analysis, it was found that the main targets for inhibiting BPH are AKT1, TNF, EGFR, STAT3 and PTGS2, which are enriched in pathways in cancer." (PMID 37446563, 2023). "We found that platelet-derived EVs from CRC patients induced PTGS2 in all four cancer cell lines at 24 h of cocultures, suggesting the contribution of a posttranscriptional mechanism." (PMID 36672299, 2023). "At baseline, HCA7 cells showed a higher expression of PTGS2 than that detected in the other four cancer cell lines, which presented comparable low gene expression (from 0.01 to 2% of that found in HCA7 cells)." (PMID 36672299, 2023). "Cyclooxygenase-2 (COX-2) and PTGS2, involved in cancer initiation and progression, were upregulated in HGF cells." (PMID 36961055, 2023). "Although multiple genes, such as ACSL4, PTGS2, NOX1, GPX4, FTH1, and SLC7A11, have been shown to be associated with ferroptosis, it is unclear how ferroptosis is genetically programmed in cancers." (PMID 35321435, 2022). "The genes MAPK14, HSP90AA1, PTGS2, and ESR1 have been linked to cancer, infection, and immune disease." (PMID 36212968, 2022). "We next sought to investigate in closer detail the kinetics of Ptgs2 transcriptional upregulation post-CTX relative to the treatment effects on cancer cell growth." (PMID 35440553, 2022). "We found that the mRNA expression of IL7R, COL22A1, ZNF185, and SRD5A2 were upregulated in cancer tissues, while PTGS2 and CLDN1 were higher in normal tissues, consistent with our previous analysis." (PMID 35813821, 2022). "We exploited this reporter cell line and devised a high throughput system to screen a comprehensive library of 1280 market-approved compounds and simultaneously compare their effects on cancer cell proliferation and Ptgs2 transcription over time." (PMID 35440553, 2022). "Surprisingly, mRNA expression of PTGS2 was specifically significantly upregulated in 3 types of cancer samples (among 30 types of cancer) including PDAC samples compared with normal samples (FC > 2, p < 0.01)." (PMID 35701649, 2022). "Our PPI network analysis identified four hub genes (SLC2A1, VEGFA, JUN, and PTGS2) enriched in the cancer-related pathways." (PMID 36482897, 2022). "MAPK14, hSP90AA1, and PTGS2 genes are associated with apoptotic biological processes, TNF signaling pathways, toll-like receptor signaling pathways, and cancer pathways." (PMID 36212968, 2022). "Instead, PGE2 levels post-treatment strictly depended on the transcriptional upregulation of Ptgs2, and accurately correlated with its basal expression levels in mouse and human cancer cells." (PMID 35440553, 2022). "As a classic inflammatory factor, PTGS2 has been found to play pleiotropic and multifaceted roles in the occurrence or promotion of various cancers and the resistance of cancer cells to radiotherapy and chemotherapy." (PMID 36203533, 2022).
cancer (continued). "Several studies have demonstrated that PTGS2 induces cancer stem cell-like activity and promotes the proliferation, angiogenesis and metastasis of cancer cells." (PMID 34336641, 2021). "Researchers have long noticed the important role of PTGS2 in the occurrence and development of cancer." (PMID 35096012, 2021). "Prostaglandin G/H synthase 2 (PTGS2) exhibits the highest degree and regulates 13 types of cancers, followed by HSP90AA1 (degree = 12), EGFR (degree = 12), and MMP2 (degree = 11)." (PMID 34248628, 2021). "PTGS2 plays a major role in promoting the proliferation, invasion, metastasis and anti-apoptosis of cancer cells through its metabolite prostaglandin E2." (PMID 34124047, 2021). "In detail, PTGS2 is the rate-limiting enzyme in prostaglandin synthesis, which induces the inflammatory environment to promote cancer development and progression." (PMID 34248628, 2021). "Further mechanism studies suggest that the up-regulation of PTGS2 gene expression in ferroptosis requires lipid peroxidation, because antioxidant vitamin E or toxic 4-HNE can inhibit or induce PTGS2 expression in cancer cells or macrophages, respectively." (PMID 33553189, 2021). "PTGS2 induces cancer stem cell (CSC)-like activity, and promotes apoptotic resistance, proliferation, angiogenesis, inflammation, invasion, and metastasis of cancer cells." (PMID 34136395, 2021). "ATX produces LPA, which activates LPA receptors on cancer cells to increase the expression of PTGS2 and inflammatory cytokines/chemokines." (PMID 34575976, 2021). "Seven upregulated genes (≥2.0-fold), Ccl24 (4.8-fold), Ccl17 (3.9-fold), S100a8 (2.9-fold), Tarm1 (2.7-fold), Anxa10 (2.4-fold), Ptgs2 (2.0-fold), and Ccl22 (2.0-fold) were detected as inflammatory and cancer-promoting genes." (PMID 34948416, 2021). "We found an inverse dependence between Chk-α and PD-L1 levels in three of the four cancer cell lines investigated that was mediated, in part, by prostaglandin-endoperoxide synthase 2 (COX-2) and transforming growth factor beta (TGF-β)." (PMID 33608051, 2021). "In colon cancer cells, TTP also promotes the downregulation of PTGS2, a potent activator of prostaglandin E2 biosynthesis, which not only promotes cancer cell proliferation, but also impairs T cell activation, thus favoring immune escape." (PMID 32932781, 2020). "This analysis showed unambiguous positive correlations between transcript levels of PTGS2, encoding for COX-2, and the levels of CP factors induced by cancer cell-intrinsic COX-2 in murine tumors pan-cancer." (PMID 33220234, 2020). "PTGS2 is undoubtedly the most studied protein of this pathway, explored in a variety of cancers and found upregulated through a variety of methods (northern blot, immunoblotting, and RT-PCR)." (PMID 33081378, 2020). "PTGS is a rate limiting enzyme in the initial step of prostaglandin (PG) synthesis, and PTGS2 is a promoter of the development of malignant tumors and inflammation." (PMID 33292329, 2020). "Significantly, prostaglandin-endoperoxide synthase 2 (PTGS2, Degree = 19) has been found to be highly expressed in many cancer types, and it contributes to tumorigenesis via the inhibition of apoptosis, increased angiogenesis, and invasiveness." (PMID 31949474, 2019). "Reportedly, the proteins Mmp12, Pparg, and Ptgs2 are related to digestive system disease and cancer." (PMID 31341536, 2019). "Within the last years, potential therapeutic application of several micro-RNA (miR) that directly regulate PTGS2 expression have been reported in several cancer." (PMID 31920649, 2019). "MMP14, MDM2, ERBB2, SKP2 and PTGS2, which were previously identified as OGs in human cancer, also have higher rate of amplification in mutation data." (PMID 31205821, 2019). "In our work, we performed a standard stratification analysis to investigate the relationship of the PTGS2 polymorphism and NSAID use with the risk of cancer following the steps below." (PMID 29552297, 2018).
cancer (continued). "PTGS2 mRNA levels were increased in both mild/moderate and severe dysplastic tissue and in morphologically normal and affected tissue from cancer patients." (PMID 25166592, 2014). "PTGS2 was the only marker out of the 24 analyzed that was more frequently methylated in CCNC than in cancer cores." (PMID 25548652, 2014). "In CRC patients, PTGS2 mRNA levels were 8–9 times higher both in morphologically normal tissue and in cancer tissue, compared to healthy individuals (P<0.0001)." (PMID 25166592, 2014). "In another study, cells from the carcinoma cell line A431 were exposed to lead ions (Pb2+) which lead to a reduction in methylation of the gene prostaglandin-endoperoxide synthase 2 (PTGS2)." (PMID 25076963, 2014). "PTGS2 mRNA levels in intestinal adenoma cases and carcinoma cases were subdivided by PTGS2 A-1195G (rs689466), PTGS2 G-765C (rs20417), and PTGS2 T8473C (rs5275) genotypes, respectively." (PMID 25166592, 2014). "On the other hand, we found that the associations between PTGS2 polymorphisms and NSAID use on cancer risk differ by the type of cancer and ethnicity." (PMID 23967159, 2013). "To date, several studies have investigated associations of the polymorphisms in the PTGS1 and PTGS2 genes and NSAID use on cancer risk; however, these studies have produced mixed results." (PMID 23967159, 2013). "In the current study, we searched the literature to determine the association between PTGS1 or PTGS2 polymorphisms and NSAID use on the risk of developing cancer." (PMID 23967159, 2013). "Accordingly, many studies have shown that PTGS2 plays a significant role in cancer development by promoting inflammation and cell proliferation." (PMID 24151976, 2013). "COX-2 and PTGS2, which are involved in cancer initiation and progression, were over expressed in HGF cells." (PMID 22912735, 2012). "Up-regulation of PTGS2 (COX2) has long been documented in various cancers and explored as a therapeutic target." (PMID 23056468, 2012). "There has been large amount of research on PTGS2 in relation to cancer, indicating a role in carcinogenesis." (PMID 21812955, 2011). "Similarly, HSP90AA1 is known to enhance tumor aggressiveness, while PTGS2 (encoding COX-2) promotes apoptosis resistance, proliferation, inflammation, and metastasis of cancer cells." (PMID 40573291, 2025). "However, only AKT1, EGFR, BCL2, HSP90AA1, and PTGS2 exhibited strong binding affinities with pomegranate compounds, which are significantly declared in affected cells to enhance cancer progression." (PMID 40573291, 2025). "Importantly, recent work has revealed the significant involvement of PTGS2 in cancer initiation, progression and metastasis." (PMID 38778047, 2024). "It was found that the core targets such as PTGS2, CXCL8, TGFB1, and STAT3 were mainly enriched in the pathways related to cancer and several inflammatory factors, and that tretinoin and PTGS2 as well as tretinoin and PTGS2, CXCL8, and STAT3 had strong binding activities." (PMID 39224778, 2024). "PTGS2 is an enzyme involved in the synthesis of prostaglandins, which are lipid mediators involved in various physiological and pathological processes, including inflammation and cancer." (PMID 38675376, 2024). "Notably, one of these clusters exhibited a significant expression of cancer‐promoting genes, encompassing Cdkn1a, Plaur, Ptgs2, Cox17, Lilrb4q, G0s2, Egr1, and Cxcl2." (PMID 39113226, 2024). "PTGS2 has been explored as a potential target for cancer research studies." (PMID 38794187, 2024). "Additionally, IL1B and PTGS2 (COX‐2), key players in inflammation, are also linked to tumour growth, angiogenesis and metastasis across various cancer types." (PMID 39629503, 2024). "CXCL8, IL1β and PTGS2 are inflammatory mediators that may play an important role in cancer progression by regulating CSC proliferation and self-renewal." (PMID 37138170, 2023).
cancer (continued). "Available data suggest that PTGS2 expression may be stimulated by ceramide accumulation, in agreement with reports of its crucial role in the response of cancer cells to cannabinoids." (PMID 38067615, 2023). "Initially, the connection between PTGS2 and angiogenesis was major in cancer and tumors." (PMID 36768450, 2023). "Finally, we confirmed the expression of PTGS2 and MMP3 in various cancer tissues and high expression of PTGS2 and MMP3 in HNSC through Human Protein Atlas (HPA) database." (PMID 36555343, 2022). "We investigated whether this upregulation was dependent on baseline PTGS2 expression in murine cancer cells." (PMID 35440553, 2022). "The R_cancer prognosis features and risk score were calculated as: MOCS1 × 1.100 − PTGS2 × 0.722 + PLEKHA8P1 × 0.409 − ZC3H12C × 0.571 + LPO × 0.575 + METTL11B × 0.294 + RP11-278A23.1 × 0.508 + RP11-452K12.7 × 0.405 − RP11-742B18.1 × 0.360 + RP11-626H12.2 × 0.787." (PMID 36419007, 2022). "The genes associated with microRNA in cancer included PTEN, CDC25A, SPY2, PLAU, E2F2, and PTGS2." (PMID 36077151, 2022). "Interestingly, TAMs (CCL2, CD86, and IL10), M1 [INOS(NOS2), IRF5, and COX2(PTGS2)] were significantly correlated with SHC1 expression in the three cancers." (PMID 35601500, 2022). "Targeting MAEL-dependent cancer stemness through PTGS2 inhibitors could be a promising therapeutic strategy for HCC management and the reversal of sorafenib resistance in particular." (PMID 35740546, 2022). "NOS2 is a synthase for protein catalytic reaction, and PTGS2 is a marker of cancer." (PMID 35696640, 2022). "Moreover, activation of STAT1 has been predicted to also upregulate expression of cancer associated genes such as IDO1 and PTGS2." (PMID 34946170, 2021). "PTGS2 encodes prostaglandin-endoperoxide synthase 2, also known as cyclooxygenase-2 (COX-2), which participates in prostaglandin synthesis, regulates inflammation, and promotes cancer progression, invasion, and migration." (PMID 34335799, 2021). "This association of PTGS2 with inflammatory cytokine expression extends to established cancer; analysis of mRNA-seq data from the Cancer Genome Atlas (TCGA) dataset showed positive correlations of PTGS2 expression with IL1B, IL6, IL8, and CXCL1 in all cancer types." (PMID 33730589, 2021). "Finally, the COX2 gene (Ptgs2 mRNA) that is required for the cancer-promoted induction of MDSC was reduced in MTL-CEBPA treated samples and significantly reduced in MTL-CEBPA +PD-1 treated samples." (PMID 34502076, 2021). "The deregulation of genes like PTGS2 (COX-2) and HPGD (15-PGDH) could be the drivers behind the prostaglandin-induced cell changes associated with cancer." (PMID 35127497, 2021). "Both SRC and PTGS2 were overexpressed in cancer tissues, and the corresponding inhibitors may be useful for ESCC treatment (p < 0.001)." (PMID 34764976, 2021). "COX-2 enzymes encoded by the PTGS2 (prostaglandin-endoperoxide synthase 2) gene catalyzes the conversion of arachidonic acid into bioreactive lipid mediator PGE2 which attributes to numerous pathophysiological processes such as inflammation and cancer." (PMID 33276479, 2020). "Potential effect of IL-4 and IL-13 (250 ng/mL, 24 h) on the expression of genes encoding proteins relevant for cancer development by facilitating angiogenesis (HIF1A and VEGFA), inflammation (PTGS2, NOS2, CCL2), and metabolic reprogramming (GLUT1, ODC1, NOS2) was evaluated." (PMID 32512917, 2020). "Cancer metastasis signaling was linked with JAK kinase, Wnt family member 9A (WNT9A), IL6, and prostaglandin-endoperoxide synthase 2 (PTGS2); whereas interleukin 1 receptor associated kinase 4 (IRAK4), and histone h3 were associated with p38MAKP signaling pathway." (PMID 30972102, 2019). "Sapropterin is a drug used in the treatment of tetrahydrobiopterin (BH4) deficiency through its specific inhibition of PTGS2; however, it is not used for the treatment of any specific type of cancer." (PMID 31690011, 2019).
cancer (continued). "Prostaglandin G/H synthase 2(PTGS2/COX-2) is closely tied with cancer." (PMID 30671125, 2018). "Our results indicate that cancer cell lines significantly upregulated genes associated with M1 monocytes including PDL1, TNF-α, IL-1β, IL-6, IL-8, CCL3, and prostaglandin-endoperoxidase synthase 2 (PTGS2)." (PMID 29668679, 2018). "To analyse the effect of NSAID use, we directly calculated the crude OR by the fixed-effect model without stratification because the PTGS2 rs5275 polymorphism was found to have no influence on the risk of cancer." (PMID 29552297, 2018). "Furthermore, the expression of Aurora-A and PTGS2 was also decreased in miR-137-overexpressing cancer cell lines." (PMID 27764771, 2016). "Furthermore, strong correlations of PTGS2 or PTGES and EGR1 mRNA levels in several cancer datasets were found, and particularly in Skrzypczak Colorectal 2 dataset, Pearson's correlation was 0.84 for PTGS2 and EGR1 and 0.647 for PTGES and EGR1 mRNA levels." (PMID 26498686, 2015). "The inactivation of the PTGS2 promoter may slow the growth of precancerous lesions and reduce the likelihood of progression to pathologically detectable cancer." (PMID 25548652, 2014). "Therefore, we performed a meta-analysis to determine the association between the polymorphisms in PTGS1 and PTGS2 and NSAID use on the risk of developing cancer." (PMID 23967159, 2013). "Therefore, we performed a meta-analysis to evaluate the association between the PTGS1 and PTGS2 polymorphisms and the effect of NSAID use on the risk of developing cancer." (PMID 23967159, 2013). "Overexpression of PTGS2, which occurs frequently in premalignant and malignant neoplasms, including hematological malignancies, together with overexpression of the prostaglandin cascade, leads to carcinogenesis through a progressive series of highly specific cellular and molecular changes." (PMID 21147609, 2011). "Both EGFR and PTGS2 (COX-2) represent promising targets for cancer prevention and treatment." (PMID 24213116, 2011). "Our data also highlight the existence of various PTGS2 haplotypes that have not been thoroughly studied and should be considered for further evaluation of risk association with cancer development and/or progression." (PMID 21059239, 2010). "PTGS2 induces the activity of cancer stem cells (CSCs) and promotes apoptotic resistance, proliferation, angiogenesis, inflammation, invasion, and metastasis of cancer cells, suggesting that inhibition of PTGS2 could play a role in the treatment of cancer." (PMID 40643495, 2025). "In our study, as the main acetaminophen targets interacting with cancer-related genes, we identified genes that encode the inducible isoform of cyclooxygenase (COX2), which catalyzes the committed step in prostaglandin synthesis involved in inflammation and mitogenesis (gene PTGS2)." (PMID 41516250, 2025). "Moreover, TFs Sp1 and NRF2 can induce PTGS2 expression in cancer cells." (PMID 38778047, 2024). "ARNT2 is overexpressed in NPC and may regulate PTGS2 to participate in the cancer process." (PMID 36203533, 2022). "TNF-α expression was observed to upregulate expression of several cancer-associated genes in the epithelial cells which include extracellular matrix (ECM) remodeling genes such as MMP9, PLAU, FN1 and ICAM1, chemokines such as CCL2, CXCL2, CXCL3 and CXCL10 and regulatory genes such as UBD and PTGS2." (PMID 34946170, 2021). "Furthermore, inflammation is also associated with cancer; suppressing chronic inflammation may inhibit cancer progression due to reduced PGE-2 and prostaglandin-endoperoxide synthase 2 (COX-2) after bromelain administration." (PMID 35056972, 2021). "In addition, the effectiveness of topical pre-application of BAY 11-7082 in inhibiting the acidic bile-induced transcriptional activation of cancer-related pro-inflammatory Il6 and Ptgs2, as similarly observed by its co-administration on HM, indicates their activation mediated by NF-κB occurs early." (PMID 32934775, 2020).